AFP (alpha fetoprotein)
Diseases named in the same sentence as AFP in open-access papers (continued):
Sharing a sentence is not in itself a finding about the gene and the disease.
cancer (continued). "Patients at more advanced cancer stages tended to have lower expression levels of PCK2, and the expression of PCK2 was also tied to age, gender, and AFP (Alpha-fetoprotein) level." (PMID 38890507, 2024). "The high levels of AFP and CA15-3 observed in the current study are suggestive of cancer and are in line with the findings of a previous study." (PMID 39659309, 2024). "Various cancer protein biomarkers like PSA, CEA, AFP, and cytokines have been detected by μPADs down to picogram per milliliter levels." (PMID 38999110, 2024). "Recent findings have demonstrated that AFP inhibition can effectively inhibit the malignant behaviors of HCC cells, suppressing their proliferation, invasion, and metastasis and inducing cancer cell apoptosis." (PMID 38660138, 2024). "In cancer diagnosis, nanobodies can detect biomarkers like Cancer Antigen 125 (CA125), Prostate-Specific Antigen (PSA), and Alpha-Fetoprotein (AFP) with high sensitivity, enabling early screening, diagnosis, and monitoring of disease progression." (PMID 39335671, 2024). "Antibody-conjugated AuNPs have been used for the specific labeling and dark-field visualization of cancer biomarkers of carcinoembryonic antigen (CEA), PSA, and alpha fetoprotein (AFP)." (PMID 37998152, 2023). "The device detected three cancer biomarkers, CEA, AFP, and CA199, with detection limits of 0.03 ng/mL, 0.05 ng/mL, and 0.09, respectively." (PMID 36979600, 2023). "The modified GCE was investigated for the simultaneous determination of the cancer biomarkers CEA and alpha-fetoprotein (AFP) by using particles of MOFs prepared from Pb(II) or Cd(II)." (PMID 37630221, 2023). "Four cancer biomarkers, namely PSA, AFP, CEA, and NSE, have been detected on substrates where the different antibodies have been immobilized sequentially on areas (1 mm × 1 mm squares) revealed by photolithography." (PMID 37241360, 2023). "Many protein and gene-based biomarkers have been used in clinical studies, such as cancer antigens (CA19–9, CA125, and CA15–3), AFP, HER2, HER4, APT, MUC 1, and ILs." (PMID 36986729, 2023). "They covalently immobilized capture antibodies on this structure and detected AFP, CA125, and CEA cancer antigens with the help of luminol-p-iodophenol-H2O2-HRP reaction by forming a sandwich method with HRP-labeled antibodies." (PMID 36979600, 2023). "Daunorubicin itself destroys G-MDSC (granulocytic myeloid-derived suppressor cells) well, but once combined with AFP it also destroys M-MDSC (monocytic myeloid-derived suppressor cells), and these are more important in cancer immunosuppression than G-MDSCs." (PMID 36768863, 2023). "For HCC model, markers including CK8, CK18, HepPar-1, Arg-1, AFP, HSP70, GPC3, CEA, CD24, CD133 and EpCAM can be used to identify cancer type and cancer progression." (PMID 37188191, 2023). "Elevated AFP level is often used as a serological marker for HCC and strongly correlates with the invasiveness of cancer cells." (PMID 37007138, 2023). "Wilson and Nie have developed a second biosensor for the detection of seven cancer biomarkers connected to different types of cancer, including CEA, human chorionic gonadotropin (hCG), alpha-fetoprotein (AFP), CA125, CA15-3, ferritin, and CA19-9." (PMID 37388583, 2023). "CFHR4 mRNA levels were inversely correlated with a cancer family history, histological grade, TNM stage, and serum AFP level of HCC patients." (PMID 36338737, 2022). "The biological activities of two short peptide segments of human alpha-fetoprotein (AFP), a major embryo-specific and cancer-related protein, have been confirmed experimentally." (PMID 35629968, 2022). "Under these conditions, cancer cell viability was reduced to 25 ± 1% and 57 ± 1% with CpGf-CMV-sr39 and CpGf-AFP-sr39, respectively." (PMID 35857843, 2022). "For ctDNA mixed with the AFP subgroup, 18 papers were studied with 1,790 HCC patients and 1,614 non-cancer participants." (PMID 36348665, 2022).
cancer (continued). "Among the 6 different types of cancers included in the current study, HCC, PAAD and CRC have relatively sensitive and specific serum tumor antigen markers: AFP for HCC, CA19-9 for PAAD and CRC, and CEA for CRC, respectively." (PMID 35105875, 2022). "In a previous study, it has been reported that the AUC of Alpha-Fetoprotein (AFP), which is a currently used cancer biomarker for HCC, is 0.646, and for ITIH4, it is 0.667." (PMID 35576868, 2022). "Spearman's rank correlation analysis was performed to assess relationships among cancer tissue, plasma PCNAP1, and plasma AFP." (PMID 35224110, 2022). "More importantly, the AFPlowAFMhigh group had a higher survival rate than the AFPhighAFMlow group (p = 0.011), indicating the importance of the reciprocal regulation between AFP and AFM in the context of cancer." (PMID 35476977, 2022). "There was a positive relationship between PCNAP1 and AFP in the plasma of HCC patients (r = 0.41, P < 0.01), and the level of PCNAP1 in plasma was also positively related to PCNAP1 in cancer tissue (r = 0.54, P < 0.01)." (PMID 35224110, 2022). "Among the proteins in blood, human epididymis protein 4 (HE4), alpha-fetoprotein (AFP) and carcinoembryonic antigen (CEA) are approved serum biomarkers for cancer detection." (PMID 36557345, 2022). "This was connected to the HCC marker alpha-fetoprotein, showing that FCN2 is involved in the development and progression of cancer." (PMID 36425563, 2022). "Our experimental evidence and the meaningful correlation with AFP support the finding that FCN2 is underexpressed in HCC and that it has prognostic value in this cancer type." (PMID 36425563, 2022). "Meanwhile, there was a positive correlation between serum AFP level and the expression of YTHDF3 in carcinoma tissue (r = 0.258, P < 0.0001)." (PMID 36471428, 2022). "According to the Technological Program on Cancer Early Detection and Treatment in 2011 in China, patients with HBV chronic infection were invited to receive ultrasound and alpha-fetoprotein (AFP) examinations directly." (PMID 35047391, 2021). "Exosomes secreted by AFP-expressing DCs (DEXAFP) induce intense immune responses based on antigen specificity, which lead to significantly delayed cancer development and increased survival rates in murine models of HCC." (PMID 34200243, 2021). "AFP inhibits the activity of NK cells and T cells by activating AFPR-positive MDSCs and promoting cancer development." (PMID 33898423, 2021). "The application of AFP-derived peptides, AFP fragments and recombinant AFP (AFP-inhibiting fragments, AIFs) to inhibit the binding of AFP to intracellular proteins or its receptors is the basis of a new strategy for the treatment of HCC and other cancers." (PMID 33898423, 2021). "Best-fitting of C(t), AFP and PIVKA-II decline was obtained setting θ1 = 30 and ψ1 = 5, which yielded a 27.1% and 5.8% reduction in neo-angiogenesis and cancer cells replication, respectively." (PMID 33922938, 2021). "Today, the most validated MRD-biomarkers remain cancer-specific antigens such as CA125, CA15.3, carcinogen embryonic antigen (CEA), alpha-feto protein (αFP), and prostate-specific antigen (PSA)." (PMID 34771526, 2021). "Other parameters estimated by the model resulted highly heterogeneous among patients, in particular the average daily rate of AFP and PIVKA-II production by cancer cells, which encompassed a 3 Log range in this cohort." (PMID 33922938, 2021). "Best fitting of C(t), AFP and PIVKA-II decline was obtained setting θ1 = 50 and ψ1 = 5, which yielded a 50.9% and 9.4% reduction in neo-angiogenesis and cancer cells replication, respectively." (PMID 33922938, 2021). "The levels of digestive tract tumor markers, including alpha-fetoprotein (AFP), carcinoembryonic antigen (CEA), and cancer antigen 19-9 (CA19-9), were within the normal range." (PMID 34646677, 2021).
cancer (continued). "By model fitting of pre-treatment AFP and PIVKA-II levels, we computed the mean lifetime of cancer cells (9.1 days) and their production rate during the initial stage (0.36/day), finding an average cancer cells doubling time of 2.7 days." (PMID 33922938, 2021). "Decreased in HCC patients, increased after hepatectomy in cancer patients and the AUCs for detecting HCC by cfDNA integrity and AFP were 0.705 and 0.605, respectively." (PMID 34660697, 2021). "AFP can bind to MUC1 and MUC4 to synergistically promote cancer cells proliferation, migration and invasion." (PMID 33718192, 2021). "The addition of AFP to ultrasound increased the sensitivity to 63% (95% CI 48–75%) for early-stage HCC, and to 97% (95% CI 91–99%) for all stages of cancer." (PMID 34372524, 2021). "Alpha-fetoprotein (AFP) is produced primarily by the liver in a developing fetus or as a result of liver damage and certain cancers." (PMID 34876963, 2021). "Serum cancer biomarkers including CEA, AFP, CA125, CA19-9 and CA15-3 have been very useful to assist cancer diagnosis and disease monitoring in various cancers 3-5." (PMID 33123272, 2020). "Protein markers like carcinoembryonic antigen (CEA), prostate specific antigen (PSA), alpha-fetoprotein (AFP), and cancer antigen 125 (CA-125) already earned their place in the diagnosis or progression of several cancer types." (PMID 32670885, 2020). "In conclusion, we have demonstrated that measuring AFP to detect HCC can improve overall and cancer-specific mortalities in patients with chronic liver disorders, even after correcting for lead times due to AFP screening." (PMID 32845895, 2020). "Specific cancer-derived proteins including carcinoembryonic antigen (CEA) and alpha-fetoprotein (AFP) are similarly detectable, as well as circulating metabolites." (PMID 32552826, 2020). "Whereas AFP and DCP are markers that are comparatively highly specific for HCC, increased serum FGF19 levels have been reported in several types of cancers." (PMID 31718608, 2019). "Cancer testis antigens and oncofetal antigens like MAGE, WT1 as well as alpha-fetoprotein are expressed in a wild range of different cancer cells, but limited in normal tissues except for embryonic cells or germ cells 161-164." (PMID 31695801, 2019). "Cancer antigen markers including carcinoembryonic antigen (CEA), carbohydrate antigen 19.9 (CA19.9), and α-fetoprotein (AFP) were all within the normal range." (PMID 31678697, 2019). "Several guidelines also recommended using additional cancer biomarkers such as CA19–9, CEA, AFP and HCG, routine blood tests including full blood count and renal function, imaging tests including CT and MRI, and the risk tools RMI and ADNEX." (PMID 31676000, 2019). "For example, α-fetoprotein (AFP) and carcinoembryonic antigen (CEA) are expressed in cancers but also upregulated in PSC-derived hepatocytes and dendritic cells, respectively." (PMID 31731794, 2019). "The coagulation profile was within the normal range, and cancer antigen markers CEA, CA19.9, and AFP were all within normal ranges." (PMID 31678697, 2019). "Investigations showed a haemoglobin of 6.5g/dl, (NR 12-14) cancer antigen 125 of 44U/ml (NR 0-35), serum beta human chorionic gonadotropin (HCG) of 0.258mIU/ml (NR 0-5) and alpha fetoprotein of 7ng/ml (NR <10)." (PMID 31692824, 2019). "Prostate-specific antigen (PSA)-, α-fetoprotein (AFP)-, carcinoembryonic antigen (CEA)-, or other cancer type-specific promoters induce efficient therapeutic gene expression in a cancer cell-specific manner." (PMID 29362367, 2018). "However, whether AFP functions in cancer cell autophagy remains unknown." (PMID 30301886, 2018). "AFP-specific CD4+ T and CD8+ T cells kill the cancer cells mainly relying on the granzyme and perforin pathways without affecting the Fas/Fasl pathways." (PMID 29805966, 2018).
cancer (continued). "Lens culinaris agglutinin reactive AFP (AFPL3%) or Lens culinaris agglutinin reactive fraction of AFP, is characterized by an elevated affinity to LCA and has been described as a more specific marker for HCC, because of its exclusive origin from cancer cells." (PMID 28077782, 2017). "In the 3-variable panel, AFP level was significantly elevated whereas the PLT count and the ALT level were decreased from non-cancer control to HCC." (PMID 28827721, 2017). "The concentrations of cancer biomarkers, such as PSA, CEA, and AFP, are typically several nanograms per milliliter." (PMID 28672780, 2017). "For instance, Chon and co-workers demonstrated the simultaneous detection of two routine cancer biomarkers (i.e., CEA and AFP) by SERS under a single excitation wavelength by exploiting the same HGNs—magnetic beads combination." (PMID 28773196, 2017). "Expressions of liver tumour markers AFP, TGF-β, M2-PK and OV-6 were significantly higher (p < 0.05) in tissues of CDE rats when compared to control showing an increased number of cancer cells during hepatocarcinogenesis." (PMID 29268718, 2017). "When comparing HCC patients with non-cancer control, univariate analysis revealed significant different expressions of WBC count, RBC count, PLT count, lymphocyte count, AFP, ALT, GGT and ALP." (PMID 28827721, 2017). "Many proteins have been identified as cancer biomarkers, including prostate-specific antigen (PSA), carcinoembryonic antigen (CEA), and α-fetoprotein (AFP)." (PMID 28672780, 2017). "It has also been reported that graphene-coated microfluidic sensors are highly sensitive to cancer biomarkers including CEA, AFP, CA153, and cancer antigen 125 (CA125)." (PMID 27916961, 2016). "We identified 15 highly connected hub genes in MEtan, including ABCA8, AFP, EGR3, EXO1, HMGA1, MT1X and VARS, which play roles as major regulators in cell-cycle regulation and cancer development." (PMID 27220887, 2016). "AFP concentrations are correlated with increased HCC tumour size but have poor sensitivity at early stages, which is insufficient for early detection of cancer." (PMID 26509158, 2015). "Since the cut-off values of AFP and CEA are low, the usefulness of the detection methods above is limited to diagnosing asymptomatic cancer at an early stage; hence, more effective, timesaving methods with high sensitivity and specificity are needed." (PMID 26251912, 2015). "α-fetoprotein (AFP) and carcinoembryonic antigen (CEA) have been frequently suggested as two valuable adjuncts in cancer diagnosis according to their high expression levels associated with cancer." (PMID 26251912, 2015). "Equally, known examples of cancer protein biomarkers (e.g., PSA, CA125, CA19-9, CEA, AFP) are frequently found in plasma at very low concentration (pg/mL-ng/mL)." (PMID 25987887, 2015). "The patient were Alpha Fetoprotein (AFP-), Carcinoembryonic antigen (CEA -) and Carcinoma Antigen (CA19-9-)." (PMID 26161177, 2015). "The Hep55.1C tumors being vascularized, expressing some human cancer and HCC markers like osteopontin, cyclin D1 and AFP, the model seemed suitable to analyze the effect of anti-cancer or anti-fibrotic drugs." (PMID 25203629, 2014). "Therefore, AFP may function in a fundamental step in the progression of AFP-positive cancer." (PMID 23382965, 2013). "AFP and CA125 are the most useful biomarkers for distinguishing patients with malignant tumor in young females." (PMID 23826706, 2013). "They include three out of six proteins approved by FDA in specific cancer diagnosis: PSA/KLK3, EGFR and AFP." (PMID 22761861, 2012). "Erroneous results due to hook effect can be observed, among others, for carcinoembryonic antigen (CEA), alpha-fetoprotein (AFP), prostate-specific antigen (PSA), prolactin, thyroglobulin, and cancer-antigen CA-125." (PMID 22666247, 2012).
cancer (continued). "Alpha-fetoprotein (AFP), a well-established biomarker in other cancers, has been reported as a potentially useful biomarker also for GEP-NENs, but its clinical relevance remains unclear." (PMID 41938105, 2026). "A prospective study enrolled 88 gastroenterology patients with unknown cancer status before sampling; conventional markers, including CEA, AFP, CA199, and CA125, were measured for comparison." (PMID 42192960, 2026). "Another study demonstrated that AFP interacts with HuR to enhance the translocation of CD47 to the cell membrane, upregulating the localization of CD47 on the surface of HCC cells and consequently inhibiting macrophages from phagocytizing these cancer cells." (PMID 40430002, 2025). "With commonly used cut‐off values for AFP (20 ng/mL) and protein induced by vitamin K absence II (PIVKA‐II, 40 mAU/mL) in clinical settings, the COMET‐LR identified 82.5% of AFP‐negative cancer cases and 74.2% of PIVKA‐II‐negative cancer cases." (PMID 40135830, 2025). "AFP can bind to AFPR-positive MDSCs, and some studies have shown that conjugating AFP to specific toxins can kill MDSCs, resulting in the release of NK cells and cytotoxic lymphocytes, thereby enhancing immune responses against cancer cells." (PMID 40430002, 2025). "In addition to AFP detection, fibroblast activation protein alpha (FAP-α) and carcinoembryonic antigen (CEA) are also important biomarkers in cancer diagnosis." (PMID 40942360, 2025). "Finally, AFP promotes EMT, a process that increases the invasive and migratory potential of cancer cells." (PMID 40430002, 2025). "Moreover, AFP has been shown to stimulate glucose transporters (GLUTs), particularly GLUT3, thereby increasing glucose uptake by cancer cells and facilitating glycolysis even under hypoxic conditions." (PMID 40430002, 2025). "The results showed that higher T stage, TNM stage, AFP levels and worse differentiation grade had greater TM9SF4 expression, which indicated that TM9SF4 expression may influence cancer development and metastasis." (PMID 40266427, 2025). "Nanozyme-SERS technology has shown promise in disease diagnosis by detecting compounds such as H2O2, uric acid (UA), glutathione (GSH), cholesterol, alpha-fetoprotein (AFP), and carcinoembryonic antigen (CEA) in serum, which are indicative of various disorders and cancers." (PMID 39859423, 2025). "Future studies would benefit from a longitudinal design with measurement of direct markers of cancer progression through imaging or laboratory assessment (eg, carcinoembryonic antigen [CEA], cancer antigen 125 [CA-125], alpha-fetoprotein [AFP], PSA, circulating transfer DNA)." (PMID 39212676, 2025). "Additionally, alpha-fetoprotein (AFP) was included, and this marked the inclusion of cancer-related biomarkers." (PMID 40218170, 2025). "Negative immunolabeling for TTF-1 and AFP excluded concurrent carcinomas of pulmonary and hepatic origin, respectively." (PMID 41321567, 2025). "Additional laboratory tests reported an alpha fetoprotein (AFP) concentration of 2.8 ng/mL (< 7.0), a remarkably high cancer antigen concentration: CA 19–9: 1000 U/mL (< 27), CA 12–5: 1679 U/mL (< 35), and a carcinoembryonic antigen (CEA) concentration of 1000.0 ng/mL (< 4.3)." (PMID 39716413, 2024). "In recent years, the discovery and development of cancer biomarkers has experienced remarkable progress, and there are now widely applicable biomarker-based assays for some cancers, such as CA199 for pancreatic cancer and AFP for liver cancer." (PMID 39850893, 2024). "Secondly, due to the limited pathological tissue, we did not conduct immunohistochemical staining of AFP levels in cancer tissue, although its expression in tissues is positively correlated with its secretion into the blood." (PMID 38408930, 2024). "Furthermore, clinicians can use AFP vaccines to generate AFP-specific CD8+ T cells and kill cancer cells." (PMID 38660138, 2024).